ALB (albumin)
Diseases named in the same sentence as ALB in open-access papers (continued):
Sharing a sentence is not in itself a finding about the gene and the disease.
nephrotic syndrome (continued). "However, serum albumin has a long half-life and is also susceptible to nonnutritional factors, such as the patient’s hydration status, infection, abnormal liver function, and nephrotic syndrome." (PMID 38431559, 2024). "Increased complement deposition in DAF−/− mice was associated with higher albuminuria and increased severity of the nephrotic syndrome, including increased BUN and reduced serum albumin, than WT animals." (PMID 37036696, 2023). "The NDKD group showed less severe proteinuria, with lower proteinuria/creatininuria (median: 2 g/g; IQR: 0.6–4.3), higher serum albumin levels (3.5 g/dl, IQR: 3.0–4.0), and lower proportion of patients with nephrotic syndrome (27.9%)." (PMID 34336286, 2021). "This Caucasian female patient presented in 2008, at the age of 17 years, with nephrotic syndrome (urine protein-creatinine ratio (UPCR) of 9 g/10 mmol (normal < 0.10 g/10 mmol), serum albumin 19 g/L (normal > 35 g/L))." (PMID 32447506, 2020). "Most patients (n = 13) had the nephrotic syndrome, median proteinuria was 4.7g/d (IQR 1.9; 12.0), and serum albumin level was 23.3 g/L (11.7; 30.9)." (PMID 28257452, 2017). "Eighty-three patients (76.9%) patients presented with nephrotic syndrome, median PCR was 6.6 g /g (IQR 3.2; 10.8) and median serum albumin was 20.0 g/L (IQR 15.9; 26)." (PMID 28257452, 2017). "The effects of dietary protein and fat on renal function-related blood and urine parameters, such as albumin, urinary protein,and inflammatory cytokines were investigated in adriamycin- (ADR) induced nephrotic syndrome rats." (PMID 21822358, 2011). "Patients who reached spontaneous remissions had less severe nephrotic syndrome than those who did not, as indicated by proteinuria and serum albumin, respectively." (PMID 41542111, 2026). "We report the case of a 72-year-old male was referred to Nephrology due to significant proteinuria (Urine albumin-creatinine ratio 14,000 mg/g) without clinical nephrotic syndrome." (PMID 40212278, 2025). "Typical nephrotic syndrome was observed in PHN rats, including significantly increased levels of 24 hr-UPro, decreased ALB, and hyperlipemia, as indicated by increases in T-CHOL, TG, HDL, and LDL beginning on the 5th day after model establishment compared to those in NC rats." (PMID 39850113, 2025). "Based on available evidence, routine use of intravenous albumin in all hospitalised children with nephrotic syndrome and oedema is not supported." (PMID 41281089, 2025). "Relevance was defined a priori as studies involving children with nephrotic syndrome who received intravenous albumin, either with or without a comparator, regardless of study design, language or outcomes reported." (PMID 41281089, 2025). "We found that the YM values in patients with nephrotic syndrome were not correlated with urinary protein and plasma albumin levels." (PMID 40848202, 2025). "TSP-1-KO mice developed ascites and weight gain, accompanied by significantly lower serum albumin levels, indicating an exacerbated nephrotic syndrome in the absence of TSP-1." (PMID 40338657, 2025). "Following a registered protocol, it evaluates the effectiveness and safety of intravenous albumin, with or without diuretics, versus no albumin in hospitalised children aged 1-18 years with nephrotic syndrome and oedema." (PMID 41281089, 2025). "Our aim was to systematically evaluate the effectiveness and safety of IV albumin, with or without diuretics, versus no albumin in hospitalised children with nephrotic syndrome and oedema, and to map excluded-but-relevant studies to identify evidence gaps." (PMID 41281089, 2025). "Collectively, these reviews highlight a striking lack of focused, high-quality evidence to guide the use of IV albumin in hospitalised children with nephrotic syndrome and significant oedema, particularly in comparison to standard treatment without albumin." (PMID 41281089, 2025).
nephrotic syndrome (continued). "Further classification into nephrotic syndrome (NS) (urinary protein > 3.5 g/day + serum albumin <30 g/L) and non-NS groups revealed elevated SLC1A5 expression in the NS group (p = 0.047)." (PMID 41189572, 2025). "A2M plays an important role in nephrotic syndrome and FSGS, being upregulated in glomerular endothelial cells and showing elevated plasma levels in nephrotic patients to balance oncotic pressure when serum albumin is lost." (PMID 39125467, 2024). "C-reactive protein decreased in relation to the increase in serum albumin due to proteinuria reduction, even if the patients did not have full-blown nephrotic syndrome." (PMID 38892620, 2024). "The results showed that the urinary protein content, the Scr, BUN, TC and TG levels were significantly increased, and the ALB level was decreased in the FSGS group, which was consistent with the typical clinical manifestations of common nephrotic syndrome in FSGS group." (PMID 38097813, 2023). "It seems feasible to employ urinary CD80 as a marker of nephrotic syndrome in adults, given that it appears to correlate with serum albumin and proteinuria, albeit lacking specificity for MCD." (PMID 36673014, 2023). "The patients with nephrotic-range proteinuria at baseline did not have a concomitant reduction in serum albumin levels and did not fulfil the criteria for nephrotic syndrome." (PMID 37978255, 2023). "Other measures of the nephrotic syndrome, including albumin and low-density lipoprotein cholesterol, were also not significantly different from baseline values at 12 months." (PMID 35005315, 2022). "He presented with a nephrotic range of proteinuria (4–6.9 g/24 h) without nephrotic syndrome (serum albumin 37 g/L)." (PMID 36371311, 2022). "Prednisolone 1.5 mg/kg every other day was started, with partial remission of the nephrotic syndrome within 2 weeks (serum albumin 3.5 g/dL, uACR 300 mg/g, and no fluid overload)." (PMID 34646728, 2021). "Gestation specific thresholds for proteinuria and serum albumin for the diagnosis of nephrotic syndrome in pregnancy have not been established." (PMID 31672135, 2019). "It is important to highlight that there is no high-quality evidence supporting use of albumin for treating nephrotic syndrome." (PMID 28443947, 2017). "Anti-PLA2R antibodies were positive in 61 % (33 of 54) of the iMN patients with nephrotic syndrome (UP ≥3.5 g/day and serum albumin ≤3.0 g/dL) and in 43 % (20 of 46) of iMN without nephrotic syndrome." (PMID 25412738, 2015). "They did not support the use of albumin in treatment of patients with nephrotic syndrome and supported the mechanism of intratubular albumin that blunts furosemide response." (PMID 22931630, 2012). "Therefore, plasma albumin levels are typically normal or near normal and patients with DD do not have nephrotic syndrome (see also section Diagnosis, above)." (PMID 39794284, 2025). "Patients with secondary FSGS may exhibit varying levels of proteinuria but, unlike primary FSGS, typically maintain normal serum albumin levels and do not develop full nephrotic syndrome." (PMID 40115110, 2025). "The strongest recommendation for treatment is in patients with severe nephrotic syndrome who are established as diuretic resistant (showing no improvement in urine output and sodium excretion) should trial supportive transfusions of albumin aiming to shift fluid to the intravascular space." (PMID 40698215, 2025). "Nephrotic syndrome is a chronic renal disease diagnosed by the presence of nephrotic range proteinuria (first-morning proteinuria ≥ 3 + on dipstick) and either hypoalbuminemia ≤ 3 g/dl or edema when serum albumin is not available." (PMID 38987746, 2024). "This problem might be addressed by employing urinary albumin clearance rather than a fixed total protein excretion threshold in defining nephrotic syndrome." (PMID 39131015, 2024).
nephrotic syndrome (continued). "Therefore, in patients with MN presenting with nephrotic syndrome, NLR may have greater predictive utility than albumin because NLR increases in the blood much faster (6–8 h) compared to the slower decrease in albumin levels (19–21 days)." (PMID 39202473, 2024). "Following a relapse of nephrotic syndrome in May 2021 (ACR 5 g/g, serum albumin concentration of 22 g/L, serum creatinine level of 168 μmol/L, anti-PLA2R at 249 IU/mL, and anti-THSD7A negative), anti-rituximab antibodies were monitored and found to be negative." (PMID 38540991, 2024). "We also like to acknowledge that serum albumin is a negative phase reactant and could be confounded in patients with nephrotic syndrome." (PMID 35973168, 2022). "FIB4-T may be able to predict more accurate prognosis than JIS and ALBI-T in case of nephrotic syndrome etc., in cases where albumin value is lower than the patients without nephrotic syndrome or in case of constitutional jaundice." (PMID 30744175, 2019). "Serum albumin level in diabetic patients with nephrotic syndrome who have generalized edema is higher than non-diabetic patients with nephrotic syndrome; because glycated albumin in diabetic patients passes easily through the capillary wall, then water shifts from plasma to interstitial space." (PMID 25340133, 2013). "Moreover, given that Ca combines with ALB in blood, non-IgAN patients that appeared to have nephrotic syndrome demonstrated decreases in serum levels of Ca after a decrease in ALB." (PMID 22738421, 2012). "In patients with relapsing nephrotic syndrome, long-term immunosuppressive drugs (e.g. cyclophosphamide, CsA, chlorambucil) are initiated after urine remission has been achieved; complete remission of serum albumin normally is not awaited." (PMID 18197423, 2008). "In addition, some studies showed that the serum anti-PLA2R antibody, anti-THSD7A antibody, anti-SOD2 antibody, and anti-ENO antibody were all negative in IMN patients with a low proportion of nephrotic syndrome at onset, high plasma albumin level, and high disease remission rate." (PMID 32117644, 2020). "In both studies, patients with glomerulonephritis had mild proteinuria (a median urine albumin-to-creatinine ratio (UACR) of 700 mg/g (interquartile range (IQR) 306–1428) in EMPA-KIDNEY and ~975 mg/g (IQR ~533–1887) in DAPA-CKD), with little or no representation of patients with nephrotic syndrome." (PMID 40429528, 2025).
breast carcinoma (323 papers, 1990 to 2026). "Previous studies have demonstrated that serum albumin levels are strongly associated with the prognoses of various malignant tumors, including breast cancer and PC." (PMID 40265018, 2025). "Studies have shown that lower serum albumin levels are associated with poorer survival rates in breast cancer and various cancers." (PMID 40904509, 2025). "For example, the neutrophil percentage to albumin ratio (NPAR) has been proposed as a dual-purpose biomarker for breast cancer risk and prognosis, aiding in early detection and personalized treatment planning." (PMID 41488918, 2025). "Regarding the role of albumin, its levels have been reported to be associated with breast cancer risk." (PMID 39548533, 2024). "Several studies have shown that low levels of ALB are associated with poor survival in patients with colorectal and breast cancer." (PMID 39075362, 2024). "Higher albumin and uric acid levels were associated with a lower risk of breast cancer development and mortality." (PMID 38791014, 2024). "We observed a suggestive mediated effect of the association between the three pollutants and breast cancer risk, through albumin, high-density lipoproteins cholesterol, low-density lipoprotein cholesterol, parathormone, and estradiol." (PMID 39548533, 2024). "In contrast, we estimated an important mediation through albumin (i.e., proportion of pure indirect effect = 28%) for the association between BaP and risk of breast cancer." (PMID 39548533, 2024). "On the other hand, the least expressed gene is ALB, which encodes albumin, and is already associated with a worse prognosis in women with breast cancer." (PMID 36982287, 2023). "Albumin levels were inversely associated with breast cancer risk, and the HRs (95% CIs) comparing the highest to the lowest quartile of albumin were 0.71 (0.51, 0.99)." (PMID 37836494, 2023). "Recently, a novel systemic inflammation score system (SIS) based on the lymphocyte to monocyte ratio (LMR) and albumin (Alb) was found to be associated with the outcome of patients with different solid tumors, including breast cancer patients." (PMID 36460981, 2022). "Higher ALB levels are associated with longer OS in patients with a number of cancers, including breast cancer." (PMID 34659642, 2021). "Another cohort study also reported that albumin and uric acid levels were associated with breast cancer risk." (PMID 34041866, 2021). "Studies demonstrated that low serum albumin was associated with poor survival and increased risk of cancer-related death in breast cancer patients." (PMID 32313183, 2020). "Several studies have reported that preoperative serum albumin levels were associated with the prognosis of breast cancer." (PMID 32590741, 2020). "Based on the results of studies, free estradiol and albumin-bounded estradiol are associated with an increased risk of breast cancer and can enhance the progression of metastatic breast cancer." (PMID 31191449, 2019). "Research over the past decades has shown an inverse relationship between albumin level and severity/risk of the progression of different cancers, including pulmonary, gastric, ovarian, and breast cancers." (PMID 31294654, 2019). "In contrast, higher isoflavone intake and serum albumin levels are associated with a lower incidence of breast cancer." (PMID 29017525, 2017). "Previous studies had confirmed that a low level of ALB was associated with poor prognosis in a variety of malignant tumors, including GC, colorectal cancer, lung cancer, and breast cancer." (PMID 28424782, 2017). "Vegetarian diet, high isoflavone intake, and high albumin levels were inversely associated with breast cancer risk (P < 0.05)." (PMID 29017525, 2017). "We found an inverse association between total serum calcium and breast cancer when comparing the fourth quartile to the first quartile (HR: 0.94, 95% CI: 0.88–0.99, p value for trend 0.04) and similar results using albumin-corrected calcium." (PMID 27608013, 2016).
breast carcinoma (continued). "Multivariable Cox regression was used to assess the association between total and albumin-corrected calcium and breast cancer risk." (PMID 27608013, 2016). "Acknowledging these facts and based on our results, it would be interesting to validate the association between SPARC expression and the benefit of albumin-bound cytotoxics in HER2-positive breast cancer." (PMID 23638089, 2013). "The aim of this study was to better assess diagnostic and prognostic significance of ischemia-modified albumin in patients with breast cancer undergoing doxorubicin chemotherapy." (PMID 24223946, 2013). "Studies have shown that higher CRP-to-albumin ratios are associated with relatively worse prognosis from early-stage to metastatic cancers, and across all types, including genitourinary, gastrointestinal, lung, and breast cancers 18-23." (PMID 37476185, 2023). "Therefore, breast cancer with high expression of Cav-1 protein is often associated with better albumin-paclitaxel treatment." (PMID 37828916, 2023). "99mTc aggregated albumin, a sterile injectable radiopharmaceutical, which has been developed for various clinical diagnostic applications, including the detection of sentinel node in breast cancer and diagnosis of other solid tumors." (PMID 34869202, 2021). "Low albumin level is associated with many malignancies, like colorectal cancer or breast cancer." (PMID 30065196, 2018). "Univariate statistical analysis found that low levels of serum albumin adversely affected survival by a statistically significant level for all stages of breast cancer while Cox regression analysis found that normal levels of albumin (>3.5 g/dL) reduced the risk of death by 72% (p = .0033)." (PMID 21176210, 2010). "Epidermal growth factor receptor (EGFR) and albumin-based systems have emerged as key platforms for targeted and efficient drug delivery in breast cancer therapy, particularly for TNBC, which lacks classical hormonal and HER2 targets." (PMID 41489768, 2026). "In the treatment of breast cancer, conventional paclitaxel treatment can only achieve a remission rate of 19%, while albumin paclitaxel can increase it to 33%." (PMID 40292112, 2025). "CPNI encompassed totalcholesterol, albumin, and lymphocytes and was initially proposed as anindependent predictor of breast cancer outcomes." (PMID 39867204, 2025). "Low albumin level isan independent poor prognostic factor for survival inearly and advanced breast cancer." (PMID 40386520, 2025). "For instance, a low prognostic nutritional index (PNI), calculated based on serum albumin (ALB) levels and total lymphocyte count (TLC), has been associated with poorer outcomes in breast cancer." (PMID 39508747, 2025). "The tolerability of varied dosing regimens, as demonstrated in this study, mirrors the observations in breast cancer studies, reinforcing the versatility of albumin-bound formulations across diverse cancer types." (PMID 40343307, 2025). "Taxanes: Taxanes are indicated for breast cancer treatment in the early-stage and advanced disease setting and include Paclitaxel (Taxol), Docetaxel (Taxotere), and Albumin-bound paclitaxel (Abraxane)." (PMID 40136358, 2025). "Paclitaxel is the first-line drug for breast cancer, and albumin paclitaxel for injection (Albumin Bound) is the first chemotherapeutic nano drug approved by Food and Drug Administration (FDA) and widely used in the clinical treatment of breast cancer." (PMID 39697556, 2024). "Univariate analysis showed that lymphocytes, neutrophils, albumin, LANR, age, TNM stage, tumor size and positive axillary lymph nodes were significantly associated with PFS (progression-free survival) in breast cancer patients (all p <0.05)." (PMID 38766483, 2024). "Like in Ferdane Danışman-Kalındemirtaş’s study, albumin-bound Fe(III)-S-Methylthiosemicarbazones was developed for breast cancer thepapy." (PMID 39483473, 2024).